TERT (telomerase reverse transcriptase)
Diseases named in the same sentence as TERT in open-access papers (continued):
Sharing a sentence is not in itself a finding about the gene and the disease.
glioma (continued). "In this study, in order to further understand the diagnostic and prognostic value of TERT promoter mutation, we examined the impact of TERT promoter mutations on survival in a series of IDH-mutated glioma cases using a large retrospective tumor cohort." (PMID 33228806, 2020). "A favorable prognostic impact of TERT promoter mutation in lower grade gliomas with an IDH mutation has been reported in several studies." (PMID 33228806, 2020). "Other surveys on different tumor types confirmed the high prevalence of TERT mutations in bladder cancer, and glioma, although they developed with different frequencies." (PMID 32810393, 2020). "Recently, the recurrent mutations at two hotspots termed as C228T and C250T in the TERT promoter have been identified in gliomas." (PMID 32509858, 2020). "ALT is the major telomere maintenance mechanism in IDHR132H mutated astrocytomas, while TERT promoter mutations were associated with IDHwildtype glioma." (PMID 31960234, 2020). "In glioma harboring telomerase reverse transcriptase (TERT) promoter mutations, TERT and EZH2 cooperate in the activation of PGC-1α, which is involved in the expression of fatty acid synthase (FASN)." (PMID 32448308, 2020). "We introduce molecular (MGMT methylation, IDH mutation, 1p/19q co-deletion, ATRX mutation, and TERT mutations) prediction methods of low-grade gliomas with imaging." (PMID 32111869, 2020). "In this study, we investigated the survival impact of TERT promoter mutations in a large cohort of 560 IDH-mutated glioma cases with detailed patient data." (PMID 33228806, 2020). "On the other hand, TERT promoter mutation was an indicator of worse outcome in MGMT-unmethylated (MGMT-unmeth) gliomas (HR = 1.86; 95% CI = 1.54–2.26; p-value < 0.001)." (PMID 32957941, 2020). "Patients who had gliomas with both IDH and TERT mutations had the best OS, and those who had gliomas with only TERTp mutations had the poorest OS." (PMID 32146731, 2020). "Here, we demonstrated that TERT mutation is associated with worse survival in well characterized cohorts and silencing of TERT expression in glioma tumor cells was associated with an enhanced response to temozolomide treatment." (PMID 32991787, 2020). "The IDH-WT diffuse gliomas in the TCGA pan-glioma cohort (with known TERT promoter mutation status) consisted of 83 cases, 71 mGBMs (85.54%) and 12 others (14.46%), all primary tumors." (PMID 33297360, 2020). "In this study, we investigated the impact of TERT promoter mutations on survival in IDH-mutated glioma cases." (PMID 33228806, 2020). "We restricted the analysis to RTK I, RTK II, MES, Midline, and MYCN18 tumors and found 500 differentially methylated CpGs compared to >10 000 differential CpGs in the unrestricted analysis underling the effect of the glioma classification over TERT mutation." (PMID 32991787, 2020). "Studies have incorporated the use of IDH mutations, 1p/19q codeletions and the TERT promoter as important alterations for glioma classification." (PMID 32999349, 2020). "In contrast, in MGMT-unmeth gliomas, TERT promoter mutation was regarded as an indicator of poor prognosis." (PMID 32957941, 2020). "Few other studies assessed ddPCR assays for detecting TERT promoter mutations but in different cancer types including melanoma and glioma and in a very small sample set." (PMID 33260905, 2020). "To determine the relevance of RBPs to gliomas with different molecular alterations, we selected samples with TERT mutation (TCGA 166, CGGA 94) in the TCGA and CGGA datasets." (PMID 32272554, 2020). "In gliomas, TERT promoter mutations lead to higher telomerase activity but the associations between TERT promoter mutations and clinical outcomes are still controversial." (PMID 32784588, 2020). "The result showed that Bladder Cancer, Glioma and Melanoma were the top three of TERT mutation frequency, while Esophagogastric cancer, Prostate cancer, and Pancreatic cancer were the last three." (PMID 32915164, 2020).
glioma (continued). "TERT promoter mutations (TERTpmut) are common in glioma and found in 80% of all primary GBM, representing one possible TMM." (PMID 31960234, 2020). "TERT promoter mutation has been heavily reported in melanoma, glioma, urothelial, thyroid, hepatocellular, and non-small cell lung cancer." (PMID 32850388, 2020). "Consistent results have also been confirmed the high prevalence of TERT mutation in bladder cancer, Glioma and Melanoma and a lower mutation frequency of breast cancer and prostate cancer, although they occurred with different frequencies." (PMID 32915164, 2020). "TERT promoter mutations are present in a high percentage of gliomas (80–90%), which makes it an interesting target gene to be studied." (PMID 31623593, 2019). "TERT promoter mutation status of these BRAFV600E-positive glioma patients was correlated to clinical parameters including gender, age, WHO grade and overall survival." (PMID 31391125, 2019). "TERT re-expression from a viral promoter partially rescued double-mutated glioma cells from the cytotoxic effect of YK-4-279." (PMID 31391125, 2019). "Most variants in the TERT promotor occurring in human gliomas are one of two changes: NM_198253.2:c.-124G>A (C228T) and NM_198253.2: c.-146G>A (C250T) located in a common SNV rs2853669." (PMID 31217899, 2019). "Among them, grade IV glioma mainly has the TERT promoter mutation accompanied by EGFR/PTEN mutation." (PMID 31850228, 2019). "Previous clinical observations and case-report studies delivered preliminary evidence that TERT promoter mutations indicate tumors with higher aggressiveness within BRAFV600E-mutated glioma." (PMID 31391125, 2019). "The TERT genetic risk variant has been associated with both glioma risk and telomere length indicating a functional effect through telomere regulation." (PMID 31842352, 2019). "We analyzed the TERT promoter mutation status in a small cohort of pediatric cases with BRAFV600E-mutated glioma (n = 8) treated at the General Hospital of Vienna." (PMID 31391125, 2019). "To further analyze this clinical finding on a broader basis, we curated a dataset of 103 BRAFV600E-mutated glioma with information on tumor grade and TERT promoter mutation from publicly available datasets." (PMID 31391125, 2019). "In order to elucidate the potential role of TERT promoter mutations in the malignant phenotype of certain BRAFV600E-mutated glioma, we curated a unique set of cell models containing nine BRAFV600E-mutant gliomas, the largest panel reported to date." (PMID 31391125, 2019). "Particularly, three robust molecular alterations, namely 1p/19q codeletion and IDH and TERT promoter mutations, were used to categorize five principal molecular groups of gliomas with distinct clinical traits and mechanisms of carcinogenesis." (PMID 31444316, 2019). "TERT promoter mutations occur during the early stage of glioma or thyroid cancers and are associated with a poor prognosis among patients with melanoma, glioma, and thyroid cancer." (PMID 29222734, 2018). "The indication of risk alleles for glioma close to TERC and TERT that are also related with telomere length suggests that telomerase is important in glioma formation." (PMID 30483309, 2018). "Although the staining was weak, nuclear immunoreactivity for TERT was also confirmed in both TERT-wildtype and mutated gliomas with the commercially available antibody for TERT (sc-7215)." (PMID 29693015, 2018).
glioma (continued). "Having confirmed the findings that all the glioma cells we analyzed showed nuclear immunostaining of TERT to various degrees, we further examined the association of the TERT promoter mutations with TERT immunoreactivity in our glioma samples." (PMID 29693015, 2018). "Recent large-scale sequencing projects have identified IDH mutation, TERT promoter mutation and 1p/19q co-deletion as cancer drivers in glioma." (PMID 29460007, 2018). "In the present study, we compared the expression of TERT protein with its mutational status in adult gliomas." (PMID 29693015, 2018). "For example, two pan-cancer studies have shown that TERT promoter mutations are present in at least six cancer types including glioblastoma, bladder, low-grade glioma, melanoma, and lung (and liver which is analyzed in one of the studies)." (PMID 30521023, 2018). "Recent research has shown that TERT mutations are observed in the most aggressive human glioma (grade IV astrocytoma) and the least aggressive diffuse human glioma (grade II oligodendroglioma) at the same time." (PMID 29871594, 2018). "In follicular and atypical thyroid adenoma as well as gliomas, TERT promoter mutations lead to significantly increased telomerase activity explaining longer telomeres observed in our cohort of mutated MLS." (PMID 29463038, 2018). "In molecular groups of gliomas that have gained the telomerase reverse transcriptase (TERT) promoter mutation, IDH mutation, and 1p/19q codeletion, rs6010620 serves as protection against glioma susceptibility in TERT mutation status." (PMID 30462709, 2018). "The variants of the TERT has been found to be associated with many types of cancers and aging-related disorders, including glioma, lung cancer, breast cancer, gastric cancer, astrocytoma and so on." (PMID 29507683, 2018). "Using our newly developed TERT-specific monoclonal antibody (TMab-6) applicable to human tissue, we found an unexpected increase in TERT expression in TERT-wildtype as well as TERT-mutated gliomas and in tumor vasculature." (PMID 29693015, 2018). "Glioma cells can avoid replicative senescence resulting from mutations in the promoter of the TERT (telomerase reverse transcriptase) gene." (PMID 29562589, 2018). "In melanoma, glioma, and thyroid cancers, TERT promoter mutations are associated with a poor prognosis." (PMID 29222734, 2018). "Thirty samples (13/16 ODGs, 17/26 GBMs) carried the c.-124C>T (TERT G228A) mutation and eight (three ODGs and five GBMs) the c.-146C>T (TERT G250A) mutation, supporting the predominance of the G228A mutation in glioma." (PMID 28915660, 2017). "Survival for patients with IDH-only mutant glioma is much longer compared with those harboring TERT promoter mutation only tumors." (PMID 28184256, 2017). "Triple-positive (IDH1 and TERT mutation with 1p19q codeletion) glioma tended to be oligodendroglioma present with much better clinical outcome compared to TERT mutation only group who is glioblastoma inclined (median overall survival 39 months VS 18 months)." (PMID 28915860, 2017). "Recently, molecular biomarkers including the 1p/19q co-deletion, BRAF mutation, IDH1/2 mutation, and TERT mutation have been widely used in the diagnosis, treatment, and prognostic prediction of gliomas." (PMID 28978019, 2017). "TERT promoter mutations have been used for classification and prognostic prediction in lower grade gliomas." (PMID 29262650, 2017). "Several meta-analyses published in 2014 associated the TERT rs2736100 polymorphism with increased glioma and lung cancer susceptibility." (PMID 28418878, 2017). "Our stratified analysis by cancer type showed that the TERT rs2736100 polymorphism correlated with increased risk of lung cancer and glioma." (PMID 28418878, 2017). "Our sample of glioma patients was restricted to tumor subtypes containing either IDH or TERT mutations exclusively." (PMID 28184256, 2017).
glioma (continued). "Recently, molecular biomarkers including 1p/19q co-deletion, BRAF mutation, IDH1/2 mutation, and TERT mutation have been widely used for glioma diagnosis, treatment, and prognosis prediction." (PMID 28978019, 2017). "It is of interest that analyses from The Cancer Genome Atlas (TCGA) identified the TERT promoter to be a somatic mutation hotspot for melanoma and bladder cancer as well as glioblastoma, glioma, liver, medulloblastoma and lung cancer." (PMID 26433962, 2016). "The prevalence of TERT promoter mutations was only 15.2% (5 of 33) in patients with grade I gliomas, whereas these mutations were found in 24.7% (40 of 162), 32.3% (41 of 127) and 38.8% (26 of 67) in patients with grade II-IV gliomas, respectively." (PMID 26556853, 2016). "A recent study showed that gliomas with TERT promoter mutations had shorter telomere length compared to TERT wild-type gliomas, which was consistent with our findings." (PMID 26556853, 2016). "In this study, we found 28.8% (112 of 389) glioma patients harbored TERT promoter mutations, which was relatively lower than previously reported." (PMID 26556853, 2016). "Considering the association of TERT promoter mutations with poor survival of primary gliomas, we investigated the effect of TERT promoter mutations on the prognosis of a cohort of 330 glioma patients in this study." (PMID 26556853, 2016). "We also found an association between glioma risk variant rs2736100 (TERT) and reduced methylation of CpG probe cg23827991 (TERT)." (PMID 27780202, 2016). "Given that 60% of tumors being TERT promoter mutation, TERT is the most frequently mutated gene in gliomas identified thus far." (PMID 27655710, 2016). "Recently, recurrent mutations at two hotspots termed C228T and C250T in the TERT promoter have been identified in diverse cancers including gliomas." (PMID 26556853, 2016). "In this study, we explored the association between TERT rs2853676 genetic polymorphisms and the prognosis of Chinese glioma patients." (PMID 27655710, 2016). "Collectively, our data suggest that glioma patients with TERT promoter mutation and long RTL are resistant to postoperative radiotherapy." (PMID 26556853, 2016). "TERT promoter mutations have been reported in glioma, breast cancer, and bladder cancer and were recently identified in thyroid malignancies." (PMID 27064992, 2016). "Numerous genetic studies have shown that glioma patients with wild type IDH or mutations in the TERT promoter have a worse prognosis." (PMID 27028997, 2016). "TERT promoter mutations in thyroid cancer and glioma were associated with increased mRNA expression and telomerase activity." (PMID 26857243, 2016). "For example, in adult gliomas, DNA methylation appears to be an alternative mechanism for TERT upregulation behind mutations, while pediatric brain tumors experience DNA hypermethylation of the TERT promoter." (PMID 27242892, 2016). "It has been reported that many TERT wild-type gliomas harbor highly frequent ATRX mutations, which induce the Alternative Lengthening of Telomeres (ALT) phenotype." (PMID 26556853, 2016). "Two hot-spot mutations (C228T and C250T) in the TERT promoter were investigated in a total of 389 glioma samples by Pyrosequencing and Sanger sequencing in this study." (PMID 26556853, 2016). "Patients who had grade II and III gliomas with only TERT promoter mutations had poorer overall survival, however, those with co-existence of both TERT and IDH mutations exhibited favorable outcomes." (PMID 27438857, 2016). "The relationship of TERT promoter mutations with patient outcomes in gliomas is revealed in most clinical studies, but more complex, and affected by other genetic alterations, TERT promoter polymorphism and tumor grades." (PMID 27438857, 2016). "IDH1/2 mutations were common in grade II-III gliomas (38–96 %), whereas TERT promoter mutations were frequently observed in oligodendrogliomas (74–83 %) and GBMs (58 %)." (PMID 27503138, 2016).
glioma (continued). "Recently, hotspot TERT promoter gene mutations have been found in gliomas, with the highest incidence in GBMs (∼60%)." (PMID 27172220, 2016). "Recent work has identified high frequency promoter point mutations in the telomerase reverse transcriptase (TERT) gene of different cancer types, including melanoma, glioma, liver and bladder cancer." (PMID 27792139, 2016). "Telomerase reactivation by recurrent somatic mutations in the TERT promoter has been identified in cancers of the central nervous system (43%), bladder (59%), thyroid (10%), and melanoma (29%)." (PMID 27240403, 2016). "While our data affirm the role of TERT promoter mutations in glial tumors, effects on transcription and telomere length emphasise the importance of telomere biology in disease genesis and outcome." (PMID 25797251, 2015). "In the present study, we investigated and show the occurrence and correlations between alterations at CDKN2A/B, 1p/19q, IDH and the TERT promoter mutations in different histological sub-types of gliomas and their effect on patient survival." (PMID 25797251, 2015). "Several previous studies reported various prognostic genes identified via mutation analyses, and ATRX and TERT promoters have recently been recognized as prognostic markers of gliomas." (PMID 26558387, 2015). "The role of TERT promoter mutations in predicting responses to adjuvant genotoxic therapies in gliomas remains relatively unexplored." (PMID 26314843, 2015). "Genome wide association studies (GWAS) of glioma have shown that TERT is one of the genes that is strongly associated with glioblastoma." (PMID 26143636, 2015). "The discovery of the TERT promoter mutations provides a possibility for (i) gaining insight into mechanistic questions in glioma development and (ii) a new biomarker and eventual therapeutic target." (PMID 25797251, 2015). "Recent reports indicate a clear subtype-specific distribution of the TERT promoter mutation in different gliomas, which in combination with IDH mutations allows classification according to their histological subgroups." (PMID 25797251, 2015). "We observed poor survival in patients with high grade gliomas that had only TERT promoter mutations." (PMID 25797251, 2015). "Somatic mutations in the promoter of TERT are found in a large proportion of adult gliomas, where they lead to aberrant binding of the GABP transcription factor and telomerase reactivation." (PMID 26646793, 2015). "The promoter mutations not only affected TERT transcription, we also for the first time in glioma observed influence on relative telomere lengths." (PMID 25797251, 2015). "We further investigated the effect of TERT promoter mutations on overall survival according to different treatment regimens in patients with high grade gliomas." (PMID 25797251, 2015). "TERT promoter mutations in low grade gliomas associated with reduced progression free survival (HR 10.2; 95% CI 1.9 – 55.9)." (PMID 25797251, 2015). "We are the first group to explore the potentially predictive role of TERT promoter mutations on response to genotoxic therapies in gliomas." (PMID 26314843, 2015). "As an aside, TERT is also interesting from the standpoint of aging (telomerase activity usually declines with aging), as one hallmark of glioma is worse prognosis of elderly patients compared to younger patients irrespective of co-morbid conditions." (PMID 26244119, 2015). "This meta-analysis suggests that the TERT genetic polymorphism rs2853676 is associated with increased risk of glioma, lung adenocarcinoma and ovarian cancer among Caucasians." (PMID 26042809, 2015). "In this report on 303 gliomas we show the highest frequency of TERT promoter mutations in gliobastomas (80%) followed by oligodendrogliomas (70%) and astrocytomas (39%)." (PMID 25797251, 2015). "TERT rs2736100 has previously been described in several GWAS to be associated to increased risk for glioma." (PMID 26143636, 2015).